PLEKHA1 (pleckstrin homology domain containing A1)
Description:
Binds specifically to phosphatidylinositol 3,4-diphosphate (PtdIns3,4P2), but not to other phosphoinositides. May recruit other proteins to the plasma membrane.
Synonyms: TAPP1
Tractability: Antibody: UniProt places it where antibodies can reach, with high confidence; its Gene Ontology location is reachable by antibodies, with high confidence. PROTAC: ubiquitination databases record sites on it; its protein half-life has been measured; a small molecule that binds it is known.
Target class: Plant homeodomain; Epigenetic regulator; Reader
Gene: Protein-coding gene on chromosome 10 (122,374,675 to 122,432,604, forward strand). Ensembl gene ENSG00000107679.
Subcellular location: Cytoplasm; Cell membrane; Nucleus
Subcellular location (Human Protein Atlas): Nucleoplasm; Cytosol
Pathways (Reactome):
Metabolism: Synthesis of PIPs at the plasma membrane
Gene Ontology:
Molecular function: PDZ domain binding; phosphatidylinositol-3,4-bisphosphate binding; protein binding; phosphatidylinositol bisphosphate binding; phospholipid binding
Biological process: B cell receptor signaling pathway; cellular response to hydrogen peroxide; establishment of protein localization; negative regulation of phosphatidylinositol 3-kinase/protein kinase B signal transduction; phosphatidylinositol 3-kinase/protein kinase B signal transduction; ruffle organization; phosphatidylinositol biosynthetic process
Cellular component: cytoplasm; cytosol; extracellular exosome; nucleoplasm; nucleus; plasma membrane; ruffle membrane
Genetic constraint (gnomAD): Loss-of-function variants: 27 observed, 38.96 expected, observed/expected ratio (o/e) 0.69, 90% interval 0.51 to 0.96. The upper end of that interval is the gene's LOEUF score, 0.96, which puts it in group 4 of 6, group 1 being the genes least tolerant of losing a copy. Missense variants: 448 observed, 460.6 expected, observed/expected ratio (o/e) 0.97, 90% interval 0.9 to 1.05. Synonymous variants: 141 observed, 158.74 expected, observed/expected ratio (o/e) 0.89, 90% interval 0.77 to 1.02.
Homologues: Orthologues: chimpanzee PLEKHA1 (99% identical), macaque PLEKHA1 (99% identical), dog PLEKHA1 (95% identical), pig PLEKHA1 (93% identical), guinea pig PLEKHA1 (93% identical), rabbit PLEKHA1 (77% identical), mouse Plekha1 (76% identical), rat Plekha1 (76% identical), tropical clawed frog plekha1 (65% identical), zebrafish plekha1a (57% identical), zebrafish plekha1b (55% identical). Paralogues in human: PLEKHA2 (46% identical).
Diseases named in the same sentence as PLEKHA1 in open-access papers:
PLEKHA1 is named in the same sentence as 23 diseases in open-access papers, as found by Europe PMC text mining. Sharing a sentence is not in itself a finding about the gene and the disease. The quoted sentences say what the papers report.
age-related macular degeneration (5 papers, 2020 to 2025). Age-related loss of vision in the central portion of the retina (macula), secondary to retinal degeneration. "For glucose metabolism, we found that the PLEKHA1 locus has been associated with type 1 and type 2 diabetes mellitus and age-related macular degeneration (AMD)." (PMID 37587247, 2023). "We found two different loci in AbdAge (rs932274, p = 1E−10) and Pancreas Accelerated Age (rs2672597, p = 3.9E−9) respectively that are close to genes implicated in age-related macular degeneration (PLEKHA1, ARMS2, HTRA1)." (PMID 35418184, 2022). "At present, the research on this gene mainly focuses on the reports related to age-related macular degeneration, and there are relatively few studies on PLEKHA1 gene in T2DM." (PMID 38152129, 2023). "Polymorphisms of PLEKHA1 are associated with various diseases, including age-related macular degeneration and type 2 diabetes, while there was no study describing the role of PLEKHA1 in tumors." (PMID 40615663, 2025).
type 2 diabetes (4 papers, 2022 to 2025). "PLEKHA1 is a GWAS locus for type 2 diabetes, adult height, and age-related macular degeneration." (PMID 35501330, 2022).
diabetes (3 papers, 2022 to 2023). "Future studies should investigate the effects of drug treatment on single cells of patients with diabetes to validate PLEKHA1 as a therapeutic target and inform the development of targeted therapies." (PMID 37143982, 2023). "Overall, our findings can aid in further investigation of the effects of drug treatment on single cells of patients with diabetes to validate PLEKHA1 as a therapeutic target and to inform the development of targeted therapies." (PMID 37143982, 2023). "Our list is supported by colocalization of genes known to lead to Mendelian forms of diabetes (e.g., SLC2A2 and WFS1) and of genes with previously demonstrated mechanisms of association with IR/T2D (e.g., METAP2, PLEKHA1 [TAPP1], FAM13A, and KLF14)." (PMID 35292083, 2022). "Interestingly, increasing evidence has shown that inflammatory pathways are common pathogenetic mediators in the natural course of both types of diabetes that involve the activity of PLEKHA1." (PMID 37587247, 2023).
Alzheimer disease (2 papers, 2022 to 2026). A progressive, neurodegenerative disease characterized by loss of function and death of nerve cells in several areas of the brain leading to loss of cognitive function such as memory and language. "However, using an extended and even more recent list of GWAS results from the European Alzheimer’s disease DNA biobank (EADB) project published as preprint reveals several new connections, i.e. for ADAM17 & USP6NL (both miR-129-5p), CTSB & EED (miR-138-5p), and ANK3 & PLEKHA1 (miR-195-5p)." (PMID 36038535, 2022).
schizophrenia (2 papers, 2022 to 2026). A major psychotic disorder characterized by abnormalities in the perception or expression of reality. "And the other 4 genes have been associated with schizophrenia (MGAT4A), Leigh syndrome (ADI1, OMIM: 256,000), congenital hypomyelinating neuropathy (PLEKHA1, OMIM: 605,253), and ID (PCK2), respectively." (PMID 36320054, 2022).
diabetic nephropathy (1 paper, 2023). "The latest study found that PLEKHA1 may represent an important biomarker that may initiate diabetic nephropathy by activating related immune cells." (PMID 38152129, 2023).
Headache (1 paper, 2022). Cephalgia, or pain sensed in various parts of the head, not confined to the area of distribution of any nerve. "Cross-trait gene-based overlap analysis identified 33 genes significantly associated (Pgene-based < 3.85 × 10−6) with migraine and T2D, and 11 genes associated with headache and T2D, with 7 genes (EHMT2, SLC44A4, PLEKHA1, CFDP1, TMEM170A, CHST6, and BCAR1) common between them." (PMID 36292730, 2022). "Similarly, PLEKHA1 and BCAR1 overlapping headache and T2D were previously associated with headache." (PMID 36292730, 2022). "Notably, seven of these genes (EHMT2, SLC44A4, PLEKHA1, CFDP1, TMEM170A, CHST6, and BCAR1) were genome-wide significant for all three traits (migraine, headache, and T2D)." (PMID 36292730, 2022).
lentivirus infection (1 paper, 2025). Virus diseases caused by the Lentivirus genus. "We generated KYSE30 and KYSE150 cell lines stably expressing Flag-tagged PLEKHA1, TACC2, different PT fusion isoforms (Pe4Te20, Pe11Te17, Pe10Te23, Pe5Te17, and Pe2Te23) or an empty vector via lentivirus infection." (PMID 40615663, 2025).
osteoporosis (1 paper, 2022). A condition of reduced bone mass, with decreased cortical thickness and a decrease in the number and size of the trabeculae of cancellous bone (but normal chemical composition), resulting in increased fracture incidence. "Additionally, the PLEKHA1 gene was prominently related to the PI3K/Akt signaling pathway, which was crucial for osteoporosis." (PMID 36360227, 2022).
PLEKHA1 also shares sentences with these, for which no sentence is quoted: atherosclerosis (1 paper); breast carcinoma (1); congenital hypomyelinating neuropathy (1); dementia (1); esophageal squamous cell carcinoma (1); Hypertension (1); hypothyroidism (1); Leigh syndrome (1); macular degeneration (1); migraine (1); myopia (1); neurological disease (1); senile cataract (1); Strabismus (1).